L1CAM (L1 cell adhesion molecule)
Diseases named in the same sentence as L1CAM in open-access papers (continued):
Sharing a sentence is not in itself a finding about the gene and the disease.
cancer (continued). "Our results showed that ALDH1, CD44, Sox2, Olig2, BMI1, LGR4, LGR5, Integrin α6, L1CAM, and ABC transporter associated with cancer stem cells were significantly downregulated." (PMID 39721005, 2025). "L1CAM cleavage and release of the soluble molecule promotes cell migration, invasion, and protection from apoptosis of cancer cells in vitro." (PMID 41039222, 2025). "In vivo, L1CAM knockout decreased cancer stem cell frequency and significantly decreased tumorigenicity." (PMID 40429728, 2025). "More than 200 studies have so far analyzed L1CAM expression in cancer by immunohistochemistry (IHC)." (PMID 41328908, 2025). "In cancer cell lines, L1CAM promotes not only epithelial-to-mesenchymal transition but also chemotherapy and anoikis resistance." (PMID 40870967, 2025). "It binds to the highly expressed L1CAM of melanoma cells and makes cancer cells spread along the vascular channels." (PMID 38737903, 2024). "L1CAM has been implicated in vascular co-option in brain metastasis, although the triggers for L1CAM expression in cancer cells remain incompletely understood." (PMID 38183514, 2024). "L1-CAM secreted by Schwann cells affected the chemotaxis of cancer cells by activating the MAP kinase signaling pathway." (PMID 39119085, 2024). "Through comprehensive genomic, epigenomic, and transcriptomic dissections, we pinpointed ARRDC5, ELF5, FIBCD1, LINC00494, NLRP7, and L1CAM as possible prognostic indicators across multiple cancer types." (PMID 39697539, 2024). "L1CAM-mediated cancer progression can be induced by proteolytic cleavage-products of full-length L1CAM (L1CAM-FL) by family members of a disintegrin and metalloproteinase (ADAM) such as ADAM10 and ADAM17." (PMID 38263290, 2024). "Schwann cells can communicate with cancer cells by secreting proteins, including L1 cell adhesion molecule (L1-CAM) and TGFβ." (PMID 39119085, 2024). "In this study, we examined the expression patterns of seven core genes (ARRDC5, ELF5, FIBCD1, LINC00494, NLRP7, L1CAM) across multiple cancer types using a combination of unpaired and paired samples, along with data from the TCGA-GTEx datasets." (PMID 39697539, 2024). "In a study, immunohistochemical analysis of PDAC tissue samples showed that L1-CAM was highly expressed in cancer cells and adjacent Schwann cells of the affected nerves." (PMID 39119085, 2024). "While we excluded participants with a history of cancer, we cannot exclude the possibility that L1CAM+ EVs came from a tissue source outside the CNS." (PMID 38438491, 2024). "L1CAM, as a cell adhesion factor, is involved in the development of the nervous system and the progression of malignant tumours." (PMID 38590656, 2024). "L1CAM, a marker of neuron-derived EVs, is upregulated in many cancer types, complicating the differentiation between AD-specific EV biomarkers and those associated with oncological conditions." (PMID 39456697, 2024). "L1CAM is a glycoprotein that occurs in the ECM and is associated with cancer development, metastases, and poor prognoses." (PMID 38263290, 2024). "The DNPs‐Gel also hold great promise for CRC treatment due to the possibility of modifying the gelatin coverage with an antibody targeting the ligand‐1 cell adhesion molecule (L1‐CAM) on cancer cells." (PMID 36459471, 2023). "It is important to note that while we used L1CAM to identify neuron-derived sEVs, it is also expressed by other cell types, including cancer cells." (PMID 37371093, 2023). "Further, L1CAM activity in disseminated cancer cells is required for perivascular spreading, or extension, and induces the activation of YAP, which, in turn, promotes the outgrowth of metastasis-initiating cells." (PMID 37835395, 2023). "L1CAM is upregulated in various types of tumors and enhances cancer cell invasiveness, leading to metastasis and resistance to chemo- and radiotherapy." (PMID 37566075, 2023).
cancer (continued). "Mint3 is also involved in the proliferation of cancer cells by regulating the expression of L1 cell adhesion molecule (L1CAM) in fibroblasts." (PMID 36831085, 2023). "Several studies have highlighted the role of L1CAM in the transendothelial migration of cancer cells, which is considered a marker and driver of metastasis-initiating cells." (PMID 37015905, 2023). "L1CAM is considered a prognostic marker in several types of cancer and has been suggested to be involved in epithelial–mesenchymal transition (EMT)." (PMID 36992411, 2023). "Fibroblasts express L1CAM in a Mint3-dependent manner, which enables CAFs to promote direct contact with cancer cells expressing integrin α5β1." (PMID 36831085, 2023). "Following extravasation, the activation of L1CAM-YAP signaling promotes the spreading of disseminated cancer cells (DCCs), displacing resident pericytes on the abluminal surface of blood vessels, leading to metastatic outgrowth." (PMID 37835395, 2023). "L1CAM is differentially expressed in a variety of human cancers and has been suggested as a promising therapeutic target." (PMID 34228897, 2022). "A handful of researchers have proposed that L1CAM represents a potential marker for cancer invasiveness and progression of CRC." (PMID 35223829, 2022). "L1CAM (L1 cell adhesion molecule) is a glycoprotein involved in cancer development, which plays a role in EMT primarily through interactions with other cell adhesion molecules, integrins, or growth factor receptors." (PMID 35600868, 2022). "Taken together, these studies suggest that the L1CAM plays a crucial role in the bidirectional cross-talk between cancer and platelets." (PMID 36387224, 2022). "The study demonstrated that cancer cells also expressed serpins, including neuroserpin and serpin B2, which inhibits stromal cell-derived plasmin – an L1CAM inactivator, and inducer of cancer cell death via FasL signaling." (PMID 36119528, 2022). "In pancreatic cancer, the cell adhesion molecule L1CAM and a metalloproteinase mediate paracrine communication between Schwann cells and cancer cells, thus promoting cancer invasion into nerves." (PMID 36499024, 2022). "In line with our results, L1CAM expression has been reported to contribute to platinum resistance in several cancer types, mainly through the modulation of intracellular signalling cascades, PI3K/Akt and MAPK pathways, affecting proliferation and apoptosis." (PMID 35429348, 2022). "Second, we show that knockout of L1CAM partially abrogates the ability of cancer cells to form spheres." (PMID 36509990, 2022). "In general, the soluble L1CAM ectodomain stimulates migration and invasion in other cancer entities." (PMID 34228897, 2022). "L1CAM endows cancer cells with enhanced tumorigenic properties and motility, which can be reversed by gene silencing as well as antibodies." (PMID 35473609, 2022). "It has been shown that L1CAM depletion abrogates the metastatic potential of T‐cell lymphoma as well as carcinoma cells, reflected by a reduction in migration and invasion of these cells in vitro and decreased formation of metastases in vivo." (PMID 34228897, 2022). "L1 cell adhesion molecule (L1CAM), a membrane glycoprotein of the immunoglobulin family, is involved in cancer progression, invasion and metastasis 17-19." (PMID 34659530, 2021). "With regard to OC, L1CAM has been recently proposed to mark, in association with CD133, a subpopulation of cancer cells with stem-like features." (PMID 34645505, 2021). "Several recent studies have revealed that the expression of L1CAM plays a pivotal role in the course of cancer development." (PMID 33710805, 2021). "One of the genes involved in axonal guidance is L1CAM, of which the expression correlates with aggressive clinical features as well as poor prognosis in many types of cancer." (PMID 35008571, 2021).
cancer (continued). "Studies have shown that the expression of Del-1 is upregulated in cancer cells; αvβ3, αvβ5, and their ligands Del-1 and L1-CAM (CD171) play essential roles in the process of cancer cell adhesion at the primary site." (PMID 34217213, 2021). "It has been shown that patients bearing L1CAM-positive cancers have poorer disease-free and overall survival." (PMID 34540651, 2021). "L1CAM has also been identified as a prognostic marker, a tool for diagnostics, and most importantly as a potential therapeutic target in cancer treatment." (PMID 33710805, 2021). "CD24 can interact with important adhesion molecules, including P-selectin, E-selectin, and L1CAM (CD171) and activate integrins, thus perhaps participating in leukocyte extravasation in inflammation and cancer metastasis." (PMID 33915986, 2021). "In several different types of cancers, including OC, EMT seems to be relevant to the acquirement and maintenance of stem cell-like characteristics and high levels of L1CAM have been associated with EMT." (PMID 31952346, 2020). "L1CAM, an adhesion molecule, mediates the spread of metastatic cells on the vasculature and additionally mediates interactions between cancer cells and endothelial cells in BM." (PMID 32059676, 2020). "This review summarizes the role of L1CAM in cancer focusing on its functional contribution to CSC pathophysiology." (PMID 32429448, 2020). "In recent years, it has been reported that L1CAM is overexpressed in various types of cancer cells and acts as a driving factor of carcinogenesis." (PMID 32742486, 2020). "We will mainly focus on the clinical relevance of L1CAM in cancer patients, and in particular on the correlation of its levels with the prognosis, the diagnosis and other clinical parameters in certain cancer types." (PMID 32429448, 2020). "The expression pattern of L1CAM in cancer and its functional role in CSC point to this molecule as a viable target for novel therapeutic strategies." (PMID 32429448, 2020). "Rescuing L1CAM expression in cancer cells through targeting of TGF-β1 reverses stemness and bears the potential to improve the still miserable prognosis of PDAC patients." (PMID 32291413, 2020). "By comparing cancer stem cell genetic profile with their non neoplastic counterpart, L1CAM emerged very frequently altered." (PMID 32429448, 2020). "The results showed that the expression of L1CAM in cancer tissues was significantly higher than that in adjacent normal tissues 34,35." (PMID 32742486, 2020). "It is possible that L1CAM, as a member of cell adhesion molecule family, can promote cancer cell trans endothelial metastasis through receptor-ligand interaction." (PMID 32742486, 2020). "L1CAM expression and proportions of old patients (>65 years), stage II−IV cancers, large tumors (>5 cm), and adjuvant therapies received were not significantly different for normal-weight and overweight/obese patients." (PMID 33232359, 2020). "This view is supported, for example, by the reported role of L1CAM in conferring chemoresistance to cancer cells (see Section 4.2), which implies that neutralizing L1CAM would restore sensitivity to conventional antitumor drugs." (PMID 32429448, 2020). "At the Center for Radiopharmaceutical Sciences of the Paul Scherrer Institute we developed the anti-L1 cell adhesion molecule (L1CAM) chimeric monoclonal antibody chCE7 for radioimmunotherapeutic (RIT) approaches to cancer." (PMID 32257947, 2020). "We found that the neural cell adhesion receptor L1CAM (L1) is a target gene of β-catenin signaling and is induced in carcinoma cells of CRC patients, where it plays an important role in CRC metastasis." (PMID 33228199, 2020). "To improve the knowledge of L1CAM as prognostic marker and therapeutic target we have reviewed the contribution of different domain-specific L1CAM forms in relation to cancer progression." (PMID 31455004, 2019).
cancer (continued). "The aims of this review are to determine the domain-specific functions of L1CAM in cancer progression and to identify the gaps in knowledge relevant for clinical implications." (PMID 31455004, 2019). "KLK5 and L1CAM play important roles in cancer progression (including cell proliferation, migration, angiogenesis, invasion, and metastasis), and their expression levels are associated with prognosis." (PMID 31572680, 2019). "This systematic review infers that L1CAM has an important role in cancer progression that can be attributed to domain-specific forms." (PMID 31455004, 2019). "Specifically, we chart its domain-specific functions in relation to cancer progression, and outline pre-clinical assays used to assess L1CAM." (PMID 31455004, 2019). "Activated plasmin releases membrane-bound FasL, which then acts as a paracrine death signal on cancer cells, and cleaves L1CAM, an important receptor for vascular co-option, and thus cancer cell survival." (PMID 31632393, 2019). "Increased expression of L1CAM was found in many cancers, including the invasive front of colorectal and pancreatic cancers." (PMID 31344926, 2019). "Soluble L1CAM thus generated promotes cancer cell migration via αVβ5 integrin in ERK and FAK dependent manner." (PMID 30792527, 2019). "It has been demonstrated that L1CAM expression in glioma tumor cells serves to promote the motility of both cancer cells and endothelial cells, thus having important implications for both metastasis and angiogenesis, respectively." (PMID 29393909, 2018). "The expression of L1CAM by various types of cancer cells is utilized to engage αVβ3 on endothelial cells." (PMID 29393909, 2018). "Elucidating genetic processes involved in the expression of L1CAM in cancers is of considerable importance." (PMID 29980240, 2018). "L1CAM expression is of prognostic value in several cancer entities and is thus considered as a promising target for therapy." (PMID 29432466, 2018). "The L1CAM Mint3-mediated expression in fibroblasts on turn stimulated in cancer cells the ERK signaling molecular pathway through integrin α5β1, thus promoting cancer cell proliferation and tumor growth." (PMID 29099748, 2017). "In cancer-associated fibroblasts (CAFs), knockdown of MT1-MMP, which promotes Mint3-mediated HIF-1 activation, or Mint3 decreased L1CAM expression." (PMID 28504692, 2017). "Taken together, Mint3/L1CAM in fibroblasts activates the ERK signalling in co-cultured cancer cells." (PMID 28504692, 2017). "L1CAM can also be detected in its soluble form (sL1CAM) in the serum and ascites fluid from patients with ovarian, uterine and other cancers." (PMID 27832351, 2017). "The association with poor outcome in patients is fully supported by the functional role of L1CAM in cancer cells, where it promotes epithelial-mesenchymal transition, motility, and invasion, as well as chemoresistance." (PMID 28134764, 2017). "Most of the studies have focused on the contribution of endothelial L1CAM to the interaction of cancer cells with the vessel wall." (PMID 28134764, 2017). "L1 cell adhesion molecule (L1CAM) has been shown to be a prognostic marker in various cancer types, and has been suggested to play a role in epithelial mesenchymal transition (EMT)." (PMID 29152102, 2017). "In accordance to recent IHC reports, L1CAM positive cancers identified by RT-PCR exhibited a significant worse disease-free (DFS) and overall survival (OS)." (PMID 27233077, 2016). "There was a significant difference in L1CAM high and low mRNA expressing cancers with regard to disease-free (p=0.002) and overall survival (p=0.008)." (PMID 27174921, 2016). "This confirms published data that up-regulation of L1CAM within cancer cells assists chemoresistance." (PMID 27174921, 2016). "L1CAM cleavage and its concomitant release of the soluble molecule have been shown to promote migration, invasion and protection from apoptosis of cancer cells." (PMID 26879132, 2016).
cancer (continued). "With regard to the clinical outcome of patients, RT-PCR was comparable to IHC and the L1CAM positive rate of cancers revealed with RT-PCR was in between the positive rates of both so far most important IHC studies." (PMID 27233077, 2016). "The prognostic significance of L1CAM expression has been addressed in many different types of cancer, including gynaecological cancers." (PMID 27028855, 2016). "Median L1CAM mRNA concentration in cancers was 0.23 (L1CAM expression relative to TBP as arbitrary units)." (PMID 27174921, 2016). "The control system of L1CAM expression in cancers is complex and is affected by both transcriptional and epigenetic mechanisms [PMID: 26111503]." (PMID 27233077, 2016). "The methylation of the L1CAM promoter was also significantly higher in cancers (median value: 31.05; Q1-Q3: 17.26-44-26) as compared to healthy endometrial tissue (median value 12.21; Q1-Q3: 10.10-13.96; p < 0.0001)." (PMID 27233077, 2016). "L1CAM promotes cell motility and is an emerging prognostic factor for metastasis in many cancer subtypes." (PMID 27028855, 2016). "The median PFS was 33 months and 18 months for patients with low and high L1CAM expressing cancers, respectively." (PMID 27174921, 2016). "The present meta-analysis was thus performed to highlight the relationship between L1CAM expression and prognosis in cancer patients." (PMID 27833079, 2016). "So far most of the results revealing L1CAM expression as an adverse prognostic factor in various cancer entities have been obtained with IHC." (PMID 27174921, 2016). "L1CAM binds to RGD-peptide-binding integrins, including integrin αvβ3 due to the presence of an RGD-peptide in its extracellular sixth Ig domain and this peptide appears to be necessary for the pro-migratory and pro-invasive effects of L1CAM in cancer cells." (PMID 27270311, 2016). "L1CAM expression has been observed in a number of cancer cell lines and tissues, and high L1CAM expression is often associated with poor prognosis and short survival times." (PMID 25860483, 2015). "These anti-malignant phenotypes of L1CAM-knockdown cancer cells were accompanied by G0/G1 cell cycle arrest and suppression of matrix metalloproteinase (MMP)-2 and MMP-9 expression and nuclear factor NF-κB activation." (PMID 25294816, 2014). "The soluble form of the L1CAM was reported to be an active factor in angiogenesis, anti-apoptosis, and cell migration in various cancers." (PMID 25294816, 2014). "In contrast, extensive necrotic regions were found in tumors excised from L1CAM-siRNA treated animals, where few ki-67-stained cancer cells were detected." (PMID 25294816, 2014). "This inhibitory effect of administrated siRNA on L1CAM expression was strictly associated to decreased IHC staining of MMP-2, MMP-9 and NF-κb in cancer cells." (PMID 25294816, 2014). "Overexpression of the transcription factor SLUG or treatment of cells with TGF-ß1 can induce or augment L1CAM levels in cancer cells." (PMID 24497324, 2014). "The control of L1CAM expression in cancers appears to be complex and is subject to both transcriptional and epigenetic regulation." (PMID 24497324, 2014). "Knowledge about genetic processes leading to the presence of L1CAM in cancers is of considerable importance." (PMID 24497324, 2014). "L1CAM is overexpressed in many human carcinomas and augments cell motility, invasion and metastasis formation." (PMID 24497324, 2014). "Prognosis of patients with L1CAM+ cancer was significantly inferior, particularly among those with diffuse-type cancers." (PMID 24422715, 2013). "Recent studies demonstrated L1CAM expression in various types of cancer, predominantly at the invasive front of tumors and metastases." (PMID 24422715, 2013). "Overexpression of L1CAM in normal and cancer cells increased motility, enhanced growth rate and promoted cell transformation and tumorigenicity." (PMID 24422715, 2013).